UNC13A (unc-13 homolog A)
Diseases named in the same sentence as UNC13A in open-access papers (continued):
Sharing a sentence is not in itself a finding about the gene and the disease.
HIV-1 infection (1 paper, 2024). The type species of lentivirus and the etiologic agent of acquired immunodeficiency syndrome (AIDS). "In addition, we confirmed that HIV-1 infection enhances cryptic exon inclusion in the FTD-ALS gene UNC13A and other genes, such as ATG4B and GSPM2, establishing a functional connection between HIV-1 infection and loss of TDP-43 function." (PMID 39242776, 2024).
Lambert-Eaton myasthenic syndrome (1 paper, 2023). Lambert-Eaton myasthenic syndrome (LEMS) is an autoimmune, presynaptic disorder of neuromuscular transmission characterized by fluctuating muscle weakness and autonomic dysfunction frequently associated with small-cell lung cancer (SCLC). "SYT2-CMS, SNAP25-CMS, VAMP1-CMS, UNC13A-CMS, RPH3A-CMS, and LAMA5-CMS are characterized by defects in the SNARE complex, and phenotypically similar to Lambert-Eaton myasthenic syndrome (LEMS)." (PMID 36835142, 2023).
Obesity (1 paper, 2025). Accumulation of substantial excess body fat. "However, four of the 24 common microglial DEGs were regulated in opposite directions by obesity in males and females (Unc13a, Atp1a3, and Arhgap33 upregulated in females and downregulated in males; Rbm47 upregulated in males and downregulated in females)." (PMID 41310161, 2025).
neurological diseases (5 papers, 2021 to 2025). "Mutations in the presynaptic IDP Unc13A (also called Munc13‐1), a key factor for regulated SV exocytosis, are causative of a variety of neurological diseases including autism‐spectrum and dyskinetic movement disorders." (PMID 37680133, 2023). "To start, UNC13A is involved in neurodevelopmental and neurological disorders which highlights its significance in neurotransmitter release and synaptic plasticity, thus offering potential therapeutic avenues for conditions such as ALS and FTD." (PMID 38188011, 2023). "Both classes of neurological diseases involved in the UNC13A and OTOF genes are reversible in clinical presentation, and the methylation levels of UNC13A and OTOF both had variability in the controlled trial of ω-3 fatty acids supplementations." (PMID 34828297, 2021). "Nevertheless, these and other transcript‐level alterations warrant further investigation as candidate biomarkers, as supported by the recent reports of STMN2 and UNC13A in ALS post‐mortem tissue and the alternative splicing events seen in the peripheral blood of other neurological disorders." (PMID 37818590, 2023).
neurodegenerative disease (4 papers, 2017 to 2025). A disorder of the central nervous system characterized by gradual and progressive loss of neural tissue and neurologic function. "For instance, a recent study published in Brain utilized the same UK Biobank cohort to estimate the high population risk of neurodegenerative disease in C9ORF72 hexanucleotide repeat expansion (HRE) carriers, while also identifying the UNC13A genotype as a key genetic modifier." (PMID 41583004, 2025). "Thus, pathological UNC13A CEs occur in vivo and are specific to neurodegenerative disease subtypes in which mislocalization and nuclear depletion of TDP-43 occurs." (PMID 35197628, 2022).
cancer (2 papers, 2015 to 2023). A tumor composed of atypical neoplastic, often pleomorphic cells that invade other tissues. "DNA methylation alterations in UNC13A, SP9, GP5, C1QL3, SP8, and VWC2 have not been previously reported in cancer." (PMID 26380585, 2015).
infection (2 papers, 2017 to 2019). The state of being infected such as from the introduction of a foreign agent such as serum, vaccine, antigenic substance or organism. "Expression of Unc13A-specific shRNA in iNs by means of lentiviral infection led to a nearly complete reduction of Unc13A protein level when tested in the mass-culture and to a complete loss of evoked NT release in autaptic hiN cultures." (PMID 30894602, 2019). "In our past study mapping expression quantitative trait loci (eQTLs) in DCs 18 hours post-infection with MTB, UNC13A was one of only 98 genes which were associated with an eQTL post-infection but not pre-infection, which we called MTB-specific eQTLs24." (PMID 28720766, 2017).
neurodevelopmental disorder (2 papers, 2025). A behavioral and cognitive disorder with onset during the developmental period that involves impaired or aberrant development of intellectual, motor, or social functions. "Among the DEGs, strong evidence of involvement in neurodevelopmental disorders was reported for 15 of them (“definitive” gene list from SysNDD, e.g., PLP1, RGS6, and SCN3A) and moderate evidence for 10 more (“limited” gene list from SysNDD, e.g., UNC13A, NMNAT2, and CHL1)." (PMID 40182141, 2025).
congenital nervous system disorder (1 paper, 2025). An abnormality of the nervous system that is present at birth or detected in the neonatal period. "The unclear mode of inheritance is associated with the GDR for UNC13A and congenital nervous system disorder, which was curated by the SD-GCEP in 2021." (PMID 40496713, 2025).
tumor (1 paper, 2023). "Further immunomodulation could be caused by UNC13A, which facilitates vesicle release and positively regulates TNF-α secretion from activated macrophages, thereby decreasing cytotoxic T-cell activity and increasing tumor growth." (PMID 37444464, 2023).
UNC13A also shares sentences with these, for which no sentence is quoted: Cognitive impairment (4 papers); autism spectrum disorder (2); congenital myasthenic syndrome (2); Parkinson disease (2); spinal muscular atrophy (2); sporadic amyotrophic lateral sclerosis (2); asthenia (1); Chorea (1); depression (1); Dystonia (1); endothelial dysfunction (1); epileptic encephalopathies (1); hereditary spastic paraplegia (1); immune disorders (1); lateral sclerosis (1); muscular dystrophy (1); neuropathic pain (1); Noonan syndrome (1); prostate carcinoma (1); sarcoma (1); speech disorder (1).